APOE (apolipoprotein E)
Diseases named in the same sentence as APOE in open-access papers (continued):
Sharing a sentence is not in itself a finding about the gene and the disease.
dementia (continued). "The epidemiological population-based study which had an average of 21 years of follow-up times before the diagnosis of dementia, showed that APOE ε4 allele carriers’ risk of dementia may be more affected by lifestyle factors such as PA, dietary fat and fish oil intake, alcohol drinking, and smoking." (PMID 28230730, 2017). "Finally most cases of AD/dementia are influenced by factors such as advancing age (65+ years), biological sex and whether one carries the ε4 allele of the APOE gene (the only genetic risk unquestionably associated with the late‐onset form of AD)." (PMID 28029715, 2017). "This allowed us to assess whether a microglial immunophenotype is associated with (i) the presence of dementia, (ii) cognition, (iii) Alzheimer’s pathology and whether (iv) the effect of APOE genotype on the risk of dementia is related to the phenotype of microglia." (PMID 27256292, 2016). "Thus, the association between APOE and cognition may, at least in part, reflect dementia-related alterations in the brain." (PMID 26252210, 2015). "Therefore, it may be that NHB have differential exposure to other dementia risk factors, rendering the relative association between APOE and dementia smaller compared to the magnitude in NHW." (PMID 25328845, 2014). "Thus, the relative impact of a gene such as APOE may be reduced among NHB if other causes of dementia are more common, or if APOE is causative only in the additional presence of other dementia risk factors that are uncommon in blacks." (PMID 25328845, 2014). "Since APOE e4 is a risk factor for both cognitive decline before the age of 60 years and dementia and is hypothesized to modify cortisol's association with cognitive function, we also conducted analyses stratified by APOE ε4 status." (PMID 24735831, 2014). "For example, just over the past decade, more than 20 dementia risk factors have been identified for sporadic Alzheimer disease, the most common cause of late-life dementia, which are in addition to advanced age and genetic determinants (for example, carrying the ApoE e4 allele)." (PMID 25356088, 2014). "They found that age, education, apolipoprotein E (ApoE) status, systolic blood pressure, body mass index, total cholesterol, and level of physical activity could be combined to produce a total score that predicts up to a 16-fold increased risk of dementia." (PMID 23437393, 2013). "Among APOE ɛ4 carriers, those with high eGDR had 14% lower incidence of dementia and a 1.77-year gap between brain age and chronological age (p-for-interaction < .001)." (PMID 41181882, 2026). "Results suggested that people with a family history of dementia and positive APOE status had increased volumes of SPARE-BA region." (PMID 41493877, 2026). "The stronger associations observed in women, especially APOE ε4 carriers, suggest that targeted screening for blood pressure metrics in midlife may offer a critical window for monitoring association with changes in cognitive function and for intervention against dementia." (PMID 41536502, 2026). "Randomisation was stratified by age, education, APOE ɛ4 carrier status, and baseline Clinical Dementia Rating." (PMID 41579901, 2026). "Significant interactions were detected between eGDR and sex/APOE ɛ4 concerning dementia onset (all p for interaction < .05)." (PMID 41181882, 2026). "Clinically, APOE-ε4 status has potential to assist in stratification for delirium prevention trials, in prediction of dementia following delirium and as a target for neuroprotective therapies during acute illness, especially if delirium is present." (PMID 41286463, 2026). "Cox proportional hazards models were used to assess the relationship between APOE genotype and dementia." (PMID 42205162, 2026). "It is also possible that APOE-induced pleiotropic genetic effects can confound the delirium–dementia relationship, also introducing bias." (PMID 41286463, 2026).
dementia (continued). "We implemented a mediation analysis to estimate how much of the APOE-ε4 genetic effect on delirium is mediated by dementia, adjusted for age and sex." (PMID 41286463, 2026). "Genetic analysis with a genome-wide association study (GWAS) has also played a role in investigating the relationship of APOE E4, dementia, and PD." (PMID 40722695, 2025). "All 4 imaging markers together explained 31% of the mediated effect of APOE ε4 on cognition and 6% on incident dementia." (PMID 40344552, 2025). "We found that TMCC2 associates with characteristic pathologies of AD in both early and late onset AD, and shows variation in apparent molecular weight according to brain region as well as by APOE and/or dementia status." (PMID 39084860, 2025). "Polymorphisms in the APOE gene are also associated with CMP, suggesting a shared role in dementia pathogenesis." (PMID 40101131, 2025). "Our findings indicate that both sex and the presence of ApoE ɛ4 allele influence the associations between late-life visit-to-visit BPV and long-term risks of dementia and cognitive decline in older adults." (PMID 41109864, 2025). "In other words, a positive family history of dementia as a prescreening question prior to APOE-genotyping would reduce the number needed to invite by a third (corrected for response-, participation-, swab-return and genotyping success ratio)." (PMID 40000321, 2025). "Specifically, the association of BPV with both dementia and CIND was attenuated in male ApoE ɛ4 carriers." (PMID 41109864, 2025). "In the case of white matter microstructural differences in a cohort aged 40–59 years, comparison of groups “near” and “far” to parental dementia onset produced larger effect sizes than comparisons based on age or APOE‐ε4 carriage." (PMID 40018326, 2025). "APOE-ɛ4 carriership is therefore often used as inclusion or enrichment criteria in dementia research and clinical trials to increase the likelihood of including cognitively normal participants with AD pathology." (PMID 40000321, 2025). "Of the genes/proteins associated with dementia, six are consistent with the results obtained from VOSviewer: APP, MAPT, APOE, ACE, IL6, and CRP." (PMID 40699836, 2025). "This study enrolled 575 AD patients, 131 patients with non‐AD dementia, and 112 cognitively normal (CN) participants, and AD patients were divided into APOE ε4 carriers and non‐carriers." (PMID 39749650, 2025). "The present AI-focused study, originally designed to examine dementia risk factors, including IHD and APOE ε4, allows us to measure APOE ε4's impact on IHD in an AI population of the upper Midwest centered in Minnesota, USA." (PMID 41282305, 2025). "Blood levels of APOE and SNAP25 have been reported to be associated with dementia and suggested as biomarkers for dementia." (PMID 40877285, 2025). "As expected, APOE ε4/ε4 was associated with advanced Braak, Thal, and CERAD stages, as well as with dementia (CDR ≥ 1)." (PMID 41268805, 2025). "As previous studies of lifestyle and APOE have focused on late‐life dementia, the interactive effects of lifestyle and APOE on midlife cognition remain unresolved." (PMID 40799136, 2025). "There was a statistically significant multiplicative interaction between CMP and the APOE genotype on the incidence of dementia (P = 0.006)." (PMID 40101131, 2025). "It enables both APOE ε4 status inference and ApoE4 protein quantitation from the same plasma sample used in routine dementia assessments." (PMID 40671162, 2025). "Indeed, a recent large-scale cross-sectional study found that APOE had very little impact on cognitive functioning in healthy aging suggesting that genetic and cellular mechanisms linked to dementia risk may be distinct from the mechanisms involved in healthy cognitive aging." (PMID 39896129, 2025). "In contrast, APOE ε2 is associated with elevated very low-density lipoprotein (VLDL) and a lower risk of dementia." (PMID 41226628, 2025).
dementia (continued). "The other 4 proteins (APOE, PDE5A, METAP1D, and TIMD4) were associated with either dementia or stroke with consistent effects as the MR analysis." (PMID 39818967, 2025). "To validate the use of ICD codes for selecting MCI/dementia participants in BioVU, we examined the association between APOE ε4 and ε2 isoforms (the strongest genetic risk and protective factors, respectively, for AD dementia) and BioVU MCI/dementia status." (PMID 39974048, 2025). "The incident dementia subgroup also had the highest proportion of APOE ε4 homozygotes (7.0%) compared to the other groups." (PMID 40568661, 2025). "APOE ε4 carriers in the ARIC cohort experienced earlier dementia onset, particularly among White participants, while our findings underscore the role of APOE ε4 with poorer episodic memory even after accounting for age, education, and sex." (PMID 41035086, 2025). "We aimed to investigate the extent to which the effect of APOE ε4 genotype on cognition and dementia is mediated by structural brain imaging markers, using data from the population-based Rotterdam Study." (PMID 40344552, 2025). "We can also find an example from the study of dementia where the informativeness of APOE ε4 as one of the best predictors of dementia varies by race." (PMID 40997045, 2025). "Cerebrospinal fluid (CSF) biomarkers and blood‐derived biomolecules were compared between AD and CN groups, between non‐AD dementia and CN groups, as well as within APOE ε4 subgroups of AD patients." (PMID 39749650, 2025). "Complete data on PSQI scores, depression, and APOE genotype was available for 963 participants (PREVENT Dementia: 658, ALFA+ [sub‐study]: 305)." (PMID 40356022, 2025). "A better understanding of the relationships between APOE, T2DM, and CVD and their contributions to dementia risk is therefore critical for the development of more effective risk reduction strategies." (PMID 39364911, 2025). "Genetic data reflected disease-specific patterns: APOE ε4 carriers were more common in the incident AD group, while family history of PD or dementia was more frequent in incident PD and AD groups, respectively." (PMID 41206819, 2025). "Genetic factors, particularly the apolipoprotein E (APOE) ε4 allele, also play a crucial role in cognitive function and are well-established risk factor for cognitive decline and dementia." (PMID 39789564, 2025). "The aim of this study was to assess the usefulness of ABCA1, ABCB7, ABCB1, APOE, CYP46A1, and LRP1 genotyping as promising dementia risk factors among a wide group of patients diagnosed first with hyperlipidemia." (PMID 41226793, 2025). "Our study supports the presence of cerebral capillopathy in both subjects with early dementia, APOE 4− (SVD) and APOE 4+ (AD probable)." (PMID 40507850, 2025). "Cox proportional hazards regression models were applied to estimate the hazard ratios (HRs) and 95% confidence intervals (CIs) of dementia risk in relation to CMP, APOE ε4 genotype, and analgesic use." (PMID 40101131, 2025). "The low apoE concentrations were correlated with dementia, cognitive impairment, and hippocampal size reduction." (PMID 41295439, 2025). "The ACE, REN, APOE, CRP, and IL6 proteins obtained through this bioinformatic approach appear to be associated with both HF and dementia." (PMID 40699836, 2025). "By contrast, the effect of APOE ε4 on dementia was stronger, yet vascular effects played a less mediating role." (PMID 40344552, 2025). "This study investigated the association between high-impact genetic variants in APOE and TREM2 and plasma levels of GFAP and NEFL in the context of incident dementia among the over 50,000 UKB participants." (PMID 40061357, 2025). "As a key mediator in lipid transport, APOE influences the complex relationship between atherosclerotic processes and neurodegenerative conditions, including dementia." (PMID 40607185, 2025).
dementia (continued). "Fourth, while previous UK Biobank studies stratified multimorbidity analyses by APOE ε4 status, we extended this by including PRS as an additional measure of genetic susceptibility to dementia." (PMID 40425445, 2025). "In APOE Ɛ4 carriers, mitochondrial enzyme activity correlates more strongly with clinical dementia severity than with the densities of neuritic plaques or tangles." (PMID 40002463, 2025). "The apolipoprotein E (APOE) ε4 allele, type 2 diabetes mellitus (T2DM), and cardiovascular disease (CVD) are well-established risk factors for dementia." (PMID 39364911, 2025). "We plan to characterize and compare the impact of each APOE genotype, and the number of APOE4 and APOE2 alleles in a person's genotype, on the incidence versus prevalence of dementia in several hundred thousand All of Us participants." (PMID 40501118, 2025). "Specifically, this review focus on the distinct associations of apolipoprotein AI and apolipoprotein E—the major components of HDL in the blood and CSF—with pathological proteins, brain integrity, cognition, and dementia progression in AD." (PMID 40353050, 2025). "This interaction among APOE, stroke, and dementia should be further investigated in humans and animal models, especially for the mechanism." (PMID 39621511, 2025). "WMHs and ≥2 microbleeds together accounted for 27% of the mediated effect of APOE ε4 on cognition and 5% on dementia." (PMID 40344552, 2025). "When combined with APOE ε4 positivity, the iPRS-DEM resulted in a five-fold increased dementia risk in memory-clinic participants." (PMID 40710902, 2025). "Developing dementia was also associated with higher BMI, total cholesterol, LDL, APOE ε4 carriership and higher CAIDE score (all <0.001)." (PMID 39863319, 2025). "Age, sex, and APOE-stratified analyses of dementia in AA participants from two cohorts revealed potential new associations." (PMID 40708016, 2025). "This group is also characterized by the lowest proportion of APOE ε4 carriers, dementia or MCI onset, and the longest time between each NP visit." (PMID 40636900, 2025). "In participants with APOE ε4 homozygosis, the overall frequencies of AD pathological diagnosis were 86% among participants with dementia, 67% in those with questionable dementia, and 38% among participants with normal cognition." (PMID 41268805, 2025). "After adjusting for demographics, education, BMI, smoking, comorbidities, inflammation, eGFR and APOE e4, ILF was associated with a higher risk of dementia (HR=1.74; 95% CI (1.34, 225))." (PMID 41502564, 2025). "We thoroughly examined moderation and stratified analyses for APOE genotype and CRP in the association between multimorbidity clusters and dementia and explored the various methodologies used to define and analyse these clusters." (PMID 40990184, 2025). "Other studies showed that elderly individuals with elevated plasma cholesterol have an increased susceptibility to dementia and AD26 compared with normocholesterolemic subjects, an effect likely mediated by defective cholesterol catabolism in APOE ε4 carriers." (PMID 41383880, 2025). "AD is the leading cause of dementia with 95% of all AD cases arising as late-onset sporadic cases (LOAD), with only 5% being linked to disease-causing genes that include apolipoprotein E (ApoE4), presenilin (PSEN), and amyloid precursor protein (APP)." (PMID 40558500, 2025). "The apolipoprotein E (APOE) ε4 allele, type 2 diabetes mellitus (T2DM), and cardiovascular disease (CVD) each are established risk factors for dementia." (PMID 39364911, 2025). "The risk of dementia and CIND was higher in diabetic patients and APOE ε4 carriers who reported low levels of moderate to vigorous PA." (PMID 40274715, 2025). "We aimed to estimate mediators of APOE ε4 on cognition and dementia through different disease markers on structural in vivo brain imaging." (PMID 40344552, 2025).
dementia (continued). "In particular, the prevalence estimates associated with age and APOE genotype in MCI and dementia at the lower and higher age extremes should be interpreted with caution." (PMID 40670684, 2025). "Clinical and genetic evidence points to variants in the ApoE gene as significant risk factors for LBD and the onset of dementia in PD patients." (PMID 39944166, 2025). "Compared with participants who were dementia-free, those who developed dementia were more likely to be older, female, APOE ε4 carriers, and to have a lower level of psychological well-being (p<0.05 for all)." (PMID 39137975, 2025). "Limitations of this study include its cross‐sectional design, self‐reporting of parental dementia diagnosis, including date and unavailability of parental APOE status." (PMID 40018326, 2025). "Together, the association between APOE SNPs and delusion and anxiety, respectively, was replicated in the ADNI dataset and these associations were beyond the effect of APOE SNPs on MCI / dementia severity." (PMID 39974048, 2025). "This is particularly important for at-risk populations such as Apolipoprotein E (APOE) ε4 allele carriers, those with a family history of dementia, and those at an early stage of cognitive decline, known as Subjective Cognitive Decline (SCD)." (PMID 40552321, 2025). "At least half of APOE‐ε4+/APOE‐ε2‐ subjects (n = 255) within 10 years of age of parental onset were amyloid positive, the proportion increasing as age of parental dementia onset is approached and then exceeded." (PMID 40018326, 2025). "Compared to participants who were Aβ−, those who were Aβ+ were older; had a lower body mass index; had greater rates of dementia and carrying APOE ε4; had lower MMSE and CDR scores; and had greater p‐tau217, p‐tau181, and GFAP levels." (PMID 39877979, 2025). "Carriage of APOE E4 variants increases the risk of cognitive impairment in PD, whereas the LRRK2 p.G2019S variant reduces the risk of hallucinations and dementia." (PMID 40926580, 2025). "We also added APOE-ε4 status as a covariate to further correct for and serve as a proxy for unrecorded dementia or MCI that can be present in population-style biobanks." (PMID 40672496, 2025). "It is known that APOE ε4 is associated with higher levels of low-density lipoprotein cholesterol (LDL-C) and total cholesterol (TC), as well as an increased risk of dementia." (PMID 41226628, 2025). "The cohort was prospectively split into low‐, medium‐, and high‐risk groups based on the presence of known risk factors (apolipoprotein E [APOE] ε4 genotype and family history of dementia [FH])." (PMID 39822299, 2025). "Clinical studies have found that elevated APOE4 gene expression increases the risk of IS, with the APOE-ε4 haplogroup being associated with dementia." (PMID 39911922, 2025). "SD-pQTLs for proteins APOE (rs157581) and SNAP25 (rs4420638) exhibited sex-dimorphic associations with dementia, indicating sex dimorphic pleiotropy in both proteins and health disorders." (PMID 40877285, 2025). "As such, APOE genotyping is currently recommended as a part of evidence-based dementia prevention and is likely to be a part of genomic-informed dementia care prior to polygenic scores which require much more optimization." (PMID 40568661, 2025). "When restricting the analyses by follow-up duration, the mediated effect of APOE ε4 on dementia was slightly higher at 7% (p value 0.134) for dementia within the first 3 years after the MRI scan date (eTable 2)." (PMID 40344552, 2025). "Participants with a family history of dementia (OR = 0.75 [95%CI = 0.55; 1.01]; p=0.063) and APOE ε4 carriers (OR = 0.79 [95%CI = 0.6; 1.04]; p=0.094) were less likely to discontinue from the study, with the association being marginally significant." (PMID 39044496, 2024). "At baseline, MCI and dementia individuals had older ages, higher percentages of APOE-ε4 carriers, shorter duration of education, and lower MoCA and MMSE scores than NC and SCD individuals." (PMID 38627753, 2024).